BRAF (B-Raf proto-oncogene, serine/threonine kinase)
Diseases named in the same sentence as BRAF in open-access papers (continued):
Sharing a sentence is not in itself a finding about the gene and the disease.
melanoma (continued). "BRAF is the most commonly mutated gene in melanoma (mutations occur in 50–70%), and mutation of this gene (a majority arising at codon 600) has been considered as the key somatic event in melanoma pathogenesis." (PMID 25784655, 2015). "Finally, the inhibition of the MAPK signalling pathway was evaluated using tumor cells, which expressed wild-type KRAS and BRAF, and in melanoma cell line BRAFV600E mutated." (PMID 26431495, 2015). "Events activating PI3K in mutated NRAS and BRAF-driven melanomas (i.e. PTEN loss), further expand the requirement of RAB7 and the roles of macropinocytosis (e.g. scavenging nutrients such as albumin and amino acids, lipids and extracellular ATP) to a broader spectrum of melanocytic lesions." (PMID 26008978, 2015). "Our results suggest that, among the high number of genetic alterations present in melanomas, a frequent oncogenic pathway is characterized by an early gain of function mutation in BRAF and a late transforming mutation in another gene responsible for chromosomal instability." (PMID 26141748, 2015). "Taken together, these results indicate that MC3181 may represent a potentialnovel therapeutic opportunity for BRAF-mutated human melanoma, while being safeand water-soluble and thus overcoming all the critical aspects of NBDHEXin vivo." (PMID 25595904, 2015). "In a subset of melanomas, amplification of the BRAF-mutant allele – which has been detected at low level in untreated cells – may be induced in response to BRAF or MEK inhibitors, also contributing to resistance to these targeted drugs." (PMID 26322273, 2015). "Furthermore, the combination regimen of trametinib and dabrafenib was recently approved by the FDA for use in melanoma patients with BRAF V600E or V600K mutations." (PMID 26262134, 2015). "However, the discovery of prevalent BRAF mutations in at least 50% of melanoma tumors led to development of BRAF-inhibitors, and other drugs targeting the MAPK pathway including MEK-inhibitors, are changing this reality." (PMID 25709607, 2015). "The initial growth in melanocytes results from atypical activation of the mitogen-activated protein kinase (MAPK) signaling pathway, which may be due to mutations of the BRAF protein in about 50% of melanoma cases." (PMID 26705496, 2015). "This unique co-regulation of endolysosomal genes was rather surprising considering that melanomas are a prototype of histopathologically heterogeneous tumors, where even the most frequent genetic alterations (i.e. oncogenic mutations in BRAF) show a varied penetrance." (PMID 26008978, 2015). "In addition, combination therapy greatly reduced angiogenesis markers in tumors of BRAF-mutated melanoma xenografts." (PMID 26299806, 2015). "Therefore, the effect of fisetin in combination with sorafenib on the PI3K signaling pathway was evaluated in BRAF-mutated melanoma cells." (PMID 26299806, 2015). "Genetic analysis of the isolated melanoma CTCs was then performed for BRAF mutation status." (PMID 25807549, 2015). "NRAS and BRAF mutations are believed to be mutually exclusive in melanoma." (PMID 26201960, 2015). "Mutations in BRAF have been implicated in some human cancers, particularly melanoma." (PMID 26312489, 2015). "Moreover, a further study that used single cell suspensions to assess BRAF mutations found 9 of 10 primary melanomas and 0 of 3 metastases to be heterogeneous." (PMID 26498143, 2015). "Perhaps the most well described BRAF-mutated cancer in humans is melanoma." (PMID 29061943, 2015). "Next, we investigated whether such unprecedented diversity of BRAF mutations is specific to melanoma or common to other cancers." (PMID 25600636, 2015). "Both VE1 and FISH data were available for 45 BRAF V600E mutated melanomas." (PMID 26141748, 2015). "Metastatic melanoma treatment is guided by mutational BRAF status." (PMID 26669314, 2015).
melanoma (continued). "The paradoxical activation of the MAPK pathway caused by BRAFV600E inhibitors could be inhibited by dual BRAF-MEK inhibition as has been observed in melanoma, but the consequence of this is expected to be more p-AKT." (PMID 25821557, 2015). "Melanomas are characterized by activating “driver” mutations in BRAF, NRAS, KIT, GNAQ, and GNA11." (PMID 26084293, 2015). "Additional evaluation is ongoing in other solid tumors, including BRAF-mutated melanoma." (PMID 26726315, 2015). "Although not examined, this suggests that aberrant MAP3K1/MAP3K2 activation could represent another means to activate the MAPK pathway in human melanoma besides the common BRAF and NRAS mutations." (PMID 26481584, 2015). "Combined BRAF/AurkA inhibition might offer a therapeutic alternative to BRAF/MEK inhibition for BRAF-mutated melanomas, while a combination of MEK/AurkA inhibitors could represent a possible option for patients without BRAF mutations." (PMID 26322273, 2015). "BRAF is a well-known frequently mutated and amplified driver in melanoma." (PMID 25572314, 2015). "In addition, several studies demonstrated that CCND1 amplifications were linked to resistance mechanisms, such as endocrine resistance in breast cancers, or BRAF inhibitor resistance in BRAF V600E mutated melanomas." (PMID 25596748, 2015). "In the subsequent phase III coBRIM trial, 495 patients with treatment-naïve BRAF V600 mutation–positive melanoma were randomized to receive vemurafenib (960 mg BID) and cobimetinib (60 mg QD 21 days on and 7 days off) (combination group) or vemurafenib and placebo (control group)." (PMID 27508107, 2015). "Importantly, BRAF inhibitors such as vemurafenib and dabrafenib have been developed as targeted therapies for melanoma patients that harbor the BRAFV600E mutation." (PMID 25890285, 2015). "It has been reported that 59% of melanomas, 18% of CRCs, 11% of gliomas, and 4% of lung adenocarcinomas and ovarian carcinomas contain BRAF mutations, which result in persistent activation of the MAPK/ERK pathway that leads to sustained proliferative signaling." (PMID 25977643, 2015). "Preclinical data suggests that BRAF activating mutations may predict sensitivity to inhibition of MEK which is supported by clinical response seen with MEK TKIs in BRAF mutated melanoma." (PMID 26018876, 2015). "Among those tumors with a BRAF mutation, NSCLCs showed a significant lower incidence of kinase-activated mutants (45 %) as compared to CRCs (85 %) and melanomas (84 %) and a higher incidence of kinase-impaired mutants or kinase-unknown mutants." (PMID 26498038, 2015). "Overall, identification of melanomas with activated alternative signaling pathways may be helpful in selecting the fraction of patients carrying BRAF mutations primarily refractory to the treatment with either a BRAF or MEK inhibitor." (PMID 25627962, 2015). "In this paper we could also show that ERβ agonists are able to decrease the proliferation of WM115 melanoma cells harboring the BRAF V600D mutation." (PMID 26225426, 2015). "The consensus panel has recognized several systemic therapies for unresectable stage IV melanoma, including high-dose IL-2, ipilimumab and, in BRAF-mutated tumors, vemurafenib, dabrafenib (BRAF inhibitors) and trametinib (MEK inhibitor), as well as referral for ongoing clinical trials." (PMID 25815245, 2015). "BRAF mutations are found in around 50% of melanomas, with V600E the most common mutation." (PMID 26562020, 2015). "Of interest, some patients with advanced melanoma can achieve prolonged CR, and our investigation suggests that some of these individuals may harbor only a BRAF mutation despite the advanced state of their disease." (PMID 25886620, 2015). "Since PLX4032 has been shown to induce arrest in G1 phase of the cell cycle in BRAF-mutated melanoma cells, we determined whether this effect also occurred in our thyroid cell lines." (PMID 24673746, 2014).
melanoma (continued). "Selective targeting of the BRAF or MEK kinases using targeted small-molecule inhibitory drugs in patients with BRAF V600E mutant melanoma has been associated with impressive clinical responses in more than half of treated patients - despite the presence of systemic disease." (PMID 25031620, 2014). "Most melanoma cell lines are susceptible to inhibition of BRAF or MEK." (PMID 24970815, 2014). "al and the commonest mutation was a single phosphomimetic substitution in the kinase activation domain (V600E) that led to activation of the MAPK pathway Although BRAF mutations have been identified in a variety of cancers, their highest incidence to the tune of almost 60% is seen in melanomas." (PMID 25005754, 2014). "This dominant activating mutation of V600E BRAF is responsible for 50-70% of melanomas." (PMID 25275294, 2014). "The frequency of BRAF mutations in primary melanomas (47%) was consistent with that observed in our previous study on 451 Italian patients with single melanoma (49%) and slightly higher than that reported in a meta-analysis on 2521 patients with cutaneous melanomas (41%)." (PMID 24885594, 2014). "BRAF mutations were detected in 109 (47.6%) of 229 primary melanomas." (PMID 24885594, 2014). "In conclusion, they proposed that Spry2 may be bypassed in melanoma cells either by downregulation of its expression in WT BRAF cells or through BRAF mutation." (PMID 24744103, 2014). "Interestingly, the knockdown of CRAF in melanoma cells with non V600E mutations in BRAF induced apoptosis through a reduction in BAD phosphorylation and Bcl-2 expression." (PMID 25422890, 2014). "Similarly to melanoma, BRAF mutations on their own induce a senescent phenotype, which manifests as benign adenomas in a mouse model of lung carcinogenesis." (PMID 24722523, 2014). "Inactivating mutations in NF1 are present in 4% of BRAF-mutated melanomas." (PMID 25344914, 2014). "Similarly, ABT-737 has been shown to sensitize melanoma cells to BRAF inhibitors only when the V600E activating mutation of BRAF is present." (PMID 26556430, 2014). "Forty percent to 60% of melanomas harbor a driver mutation, mainly V600E or V600K, in BRAF gene." (PMID 25501056, 2014). "Moreover, in melanomas, miR-193a, miR-338, and miR-565 were shown to be underexpressed in patients with a BRAF mutation." (PMID 24736504, 2014). "Indeed, oncogenic MAPK signalling through ERK (RAS-RAF-MEK-ERK) is constitutively activated in the majority of melanomas with aberrant activation frequently stemming from activating mutations in BRAF." (PMID 25168062, 2014). "Mutations in BRAF-oncogene are responsible for continuous growth in 60% of melanoma’s." (PMID 25593913, 2014). "Interestingly, the BRAF fusions in melanoma are exclusive of other known oncogenic events such as BRAF and NRAS mutations." (PMID 25204415, 2014). "It is mutated in a significant number of melanomas, including those with BRAF inhibitor resistance." (PMID 24970815, 2014). "Focusing on BRAF mutations only, about one third of patients presented discrepant mutation patterns between first and second primary melanomas (34/107; 31.8%); such a discrepancy was even higher when comparing first and third or fourth primary tumors (6/15; 40%)." (PMID 24885594, 2014). "In addition, NF1 mutations or suppression occur in human melanomas that harbor concurrent BRAF mutations." (PMID 24743024, 2014). "Therefore, the inhibition of CRAF is efficacious in melanoma cells harboring the RAS or BRAF mutation, except for V600E." (PMID 25422890, 2014). "Vemurafenib was approved for the treatment of BRAF-mutated melanoma in 2012 after a phase III trial that reported a 0.37 hazard ratio for death in patients with BRAF mutations taking vemurafenib compared with dacarbazine, and a phase II trial showing 15.9 month median survival." (PMID 25198196, 2014). "Somatic NF1 mutations have also been reported in melanoma specimens harboring BRAF mutations." (PMID 25026295, 2014).
melanoma (continued). "Compared with DTIC alone, ipilimumab in combination with DTIC has been shown to improve OS in an RCT in patients with previously treated metastatic melanoma, while vemurafenib improved OS and PFS in an RCT in patients with previously untreated melanoma harboring the V600 BRAF mutation." (PMID 25502446, 2014). "PDGFRα up-regulation in human melanoma cells harboring the BRAF(V600E) mutation is shown for the first time to be associated with the loss of their sensitivity to the anti-proliferative and pro-apoptotic activity of the BRAF-I vemurafenib both in vitro and in vivo." (PMID 24732172, 2014). "BRAF mutation is the most common event, occurring in about 50% of melanomas." (PMID 26328215, 2014). "Importantly, over half of melanomas harbor a mutation in the BRAF gene that leads to constitutive signaling down the MAPK pathway and multiple subsequent deleterious effects." (PMID 29250602, 2014). "Furthermore, the presence of several distinct BRAF gene mutations in the same melanoma tissue sample has been reported." (PMID 25265970, 2014). "By employing Boyden chamber cell invasion assay, we assessed whether treatment of BRAF mutated melanoma cell lines (such as A375, SK-MEL-28 and RPMI-7951) with fisetin inhibits their invasive potential." (PMID 24466036, 2014). "Moreover, 90% of melanomas containing the activating mutations in BRAF produce active mutant BRAFV600E protein." (PMID 24967732, 2014). "Melanoma is the malignancy with the highest prevalence of BRAF gene mutations." (PMID 25265970, 2014). "Moreover, considering that approximately half of melanomas that arise in the skin present a BRAF gene mutation, the FDA approved in 2013 the use of two new drugs, Tafinlar (dabrafenib) and Mekinist (trametinib), for patients with unresectable melanoma." (PMID 25317253, 2014). "Approximately 90% of melanomas harbor a point mutation in BRAF, NRAS or cKIT." (PMID 25516806, 2014). "The addition of hepatocyte growth factor (HGF) to BRAF-mutated melanoma cell lines confer resistance to BRAFi, hence stromal cells producing large amounts of HGF may be responsible for intrinsic resistance to therapy with BRAFi." (PMID 25344914, 2014). "40-60% melanoma patients carry BRAF mutations that activate MAPK signaling." (PMID 24884660, 2014). "Over 60% of melanomas harbor mutations in the BRAF and NRAS genes." (PMID 24550252, 2014). "The canonical example, of course, is the use of imatinib in the treatment of chronic myelogenous leukemia harboring the BCR/ABL rearrangement.A more recent example is the remarkable success of BRAF inhibitors in the treatment of malignant melanomas with BRAF V600E mutations." (PMID 25286031, 2014). "Interestingly, we determined that FO-1 cells had the common melanoma associated BRAF codon 600 V>E mutation (see MM), which renders BRAF constitutively active, whereas PT4 and MM1 cells were wild type in this same region." (PMID 24587218, 2014). "Nevertheless, more than half of melanomas express the mutationally activated BRAF (V600E, the most prevalent genetic alteration) oncoprotein, which triggers the BRAF-MEK-ERK signaling pathway (MAPK pathway), a key regulator of proliferation and differentiation." (PMID 24634165, 2014). "In addition, fisetin also inhibited the protein expression of fibronectin, an extra cellular matrix protein involved in cell adhesion and migration in BRAF mutated melanomas." (PMID 24466036, 2014). "The protein kinase BRAF is mutated in about half of all melanomas." (PMID 24482671, 2014). "Approximately 90% of all identified BRAF mutations that occur in human cancer are a T1799A transversion mutation in exon 15, which results in a V600E amino acid substitution T1799A alteration (V600E mutation) accounts for 70 to 90% of BRAF mutant melanoma patients." (PMID 25037456, 2014).
melanoma (continued). "The detection of BRAF mutations was likewise significantly associated with unfavorable survival (p = 0.013) and represented an additional independent prognostic factor for melanoma patients with thin primary tumors (HR 11.6; p = 0.034)." (PMID 24475086, 2014). "In a small subset of BRAF mutated melanoma patients, this alteration may similarly contribute to intrinsic resistance." (PMID 25344914, 2014). "Interestingly, melanomas that are wild type for both BRAF and NRAS have almost five times higher mutational loads than tumors where one of these oncogenes is mutated." (PMID 24743024, 2014). "BRAF mutations were detected in 55 of 103 cases (53.4 %) of melanoma nodal metastases." (PMID 24866436, 2014). "Moreover, even appropriately selected patient populations exhibit a poorly explained range of clinical responses, such as the ~60% response rate in BRAF mutated melanoma patients, which currently limit the effectiveness of even the most targeted approaches." (PMID 24607840, 2014). "There is growing evidence that oncogenic BRAF contributes to immune escape, and that targeting this mutation with BRAF inhibitors (BRAFi) may make melanoma tumors more immunogenic." (PMID 25941608, 2014). "Overall, about 50% of melanomas of all clinical types have mutations in BRAF." (PMID 24743024, 2014). "Somatic point mutations in the BRAF gene have been found in approximately 50% of melanomas." (PMID 26328215, 2014). "To establish whether p.V600_K601delinsD BRAF mutation-positive melanoma might be sensitive to treatment with vemurafenib, we performed a crystal structure analysis of BRAF proteins using Sybyl®-X software (Tripos, MO, USA)." (PMID 25265970, 2014). "High prevalence of genetic mutations causing altered signaling pathways in human cancer has spurred development of targeted drug therapy focusing on inhibition of intracellular kinases such as mutated BRAF, which is also commonly found in melanoma, ovarian, and colorectal cancers." (PMID 24673746, 2014). "The concept of autophagy dependence may also be applicable to human melanoma cells with RAS-MEK activation driven by mutations in BRAF V600E." (PMID 23383069, 2013). "Targeted treatment of BRAF V600E mutation is in use in advanced melanoma." (PMID 24298448, 2013). "Molecular profiling of tissues from different human cancers has shown that mutations of the BRAF gene at locus 1799 (amino acid 600) are the second most common mutations in human cancers, found in 40% of papillary thyroid carcinomas and 40–60% of melanomas." (PMID 23717811, 2013). "The fact that oncogenic BRAF mutations are frequent in “dysplastic nevi”, congenital nevi, common nevi and especially in growing nevi has challenged the role of BRAF mutations for the development of melanoma in particular and the model of stepwise tumor progression in general." (PMID 23861977, 2013). "Importantly, we found that both wild type and mutated-BRAF melanoma differentiated cells, were exquisitely sensitive to the drug, as indicated by the high fraction of sub-diploid cells detected in treated samples stained with Propidium Iodide." (PMID 24238212, 2013). "This NRAS/BRAF signaling pathway has attracted considerable attention as a target for anticancer therapy because of its high frequency of mutations and its important role in melanoma disease." (PMID 24416617, 2013). "The outstanding importance of the RAS/RAF signaling pathway is documented by the observation that BRAF and NRAS mutations—exclusively NRAS or BRAF is mutated in a tumor—together are found in over 80% of melanomas and by inhibitors of mutated BRAF that are clearly effective in melanoma therapy." (PMID 23634303, 2013).